MSLN (mesothelin)
Diseases named in the same sentence as MSLN in open-access papers (continued):
Sharing a sentence is not in itself a finding about the gene and the disease.
ovarian carcinoma (continued). "For example, Rump and colleagues showed that binding of MUC16 to membrane-bound mesothelin mediated cancer cell adhesion in ovarian cancer and that the mesothelin-MUC16 interaction might result in the intraperitoneal dissemination of tumors." (PMID 24988079, 2014). "In addition to mesothelioma, C-ERC/mesothelin is also expressed in ovarian cancer, pancreatic ductal adenocarcinoma, breast cancer, colorectal cancer and esophageal adenocarcinoma." (PMID 24146039, 2014). "MSLN is hypothesized to be involved in cell adhesion and signaling and to contribute to the metastasis of ovarian cancer to the peritoneum by binding CA125." (PMID 23590973, 2013). "Several studies have demonstrated overexpression of mesothelin (a glycoprotein present on mesothelial cells lining the pleura, peritoneum, and pericardium) in most epithelial ovarian cancers and have suggested the eligibility of mesothelin as a target for cancer therapy." (PMID 23319948, 2012). "Furthermore, silencing MSLN by a lentivirus expressing anti-mesothelin microRNA (miRNA) was also found to significantly reduce the viability and invasiveness of ovarian cancer cells." (PMID 22485139, 2012). "In models such as ovarian cancer, analyses of correlation between MSLN expression, pathological variability and clinical outcomes indicated that high MSLN expression was positively associated with chemo-resistance in epithelial ovarian carcinoma patients and short patient survival time." (PMID 22485139, 2012). "Moreover, 42% of patients with early stage ovarian cancer had elevated mesothelin in urine compared to only 12% of patients who had elevated mesothelin in serum, suggesting the potential of mesothelin as an early detection biomarker." (PMID 23319948, 2012). "We report here that gene specific silencing for Mesothelin by distinct methods (siRNA and microRNA) decreased viability of cancer cells from different origins such as mesothelioma (H2373), ovarian cancer (Skov3 and Ovcar-5) and pancreatic cancer (Miapaca2 and Panc-1)." (PMID 22485139, 2012). "In addition, mesothelin autoantibodies were detected in the sera of patients whose tumors were positive for mesothelin in ovarian cancer." (PMID 21801396, 2011). "Indeed, mesothelin is shed into the circulation and is one of a few specific serum markers for ovarian cancer." (PMID 21801396, 2011). "However mesothelin is highly expressed in ovarian cancer, mesotheliomas and to a lesser extent in other cancers such as pancreatic, lung, and stomach." (PMID 21801396, 2011). "Mesothelin is a well characterized biomarker for ovarian cancer in human." (PMID 21801396, 2011). "Mesothelin may be an emerging marker for diagnosis and target-based therapy in ovarian epithelial cancers." (PMID 19293794, 2009). "Future gene therapy directed towards enhancing mesothelin expression in cancer cells might offer a new treatment strategy for ovarian cancer patients." (PMID 19293794, 2009). "It was suggested early on that mesothelin might be involved in adhesion and particularly in adhesion and spread of ovarian cancer cells throughout the mesothelial lining of the peritoneal cavity." (PMID 19128473, 2009). "Our SQ RT–PCR and QRT RT–PCR analyses confirmed earlier reports that mesothelin was expressed in cancerous tissues of ovarian carcinomas, suggesting that mesothelin could be an ideal marker for cancer diagnosis and target-based therapy." (PMID 19293794, 2009). "Both mesothelin and kallikrein 10 may complement CA 125, increasing the prospect of detecting ovarian cancer at an early, curable stage." (PMID 15199385, 2004). "Notably, MSLN was previously related to epithelial malignancies and ovarian cancer." (PMID 38256043, 2024).
ovarian carcinoma (continued). "Surprisingly, recent research found mesothelin (MSLN), a glycosylphosphatidyl inositol-linked membrane glycoprotein, is present at significantly lower levels in mesothelial cells of the pleura, peritoneum, and pericardium of healthy persons than several cancer types, including ovarian cancer." (PMID 38694508, 2024). "As a single marker, mesothelin does not apply to the diagnosis of ovarian cancer, but it could complement standard diagnostic methods based on ultrasound and currently used tests or algorithms (CA125, OVA1, ROMA) and significantly improve their sensitivity." (PMID 37238197, 2023). "T cells containing an anti-mesothelin single-domain antibody fused to a component of the endogenous T cell receptor signaling complex exhibit notable toxicities but encouraging clinical responses in patients with treatment-refractory mesothelioma and ovarian cancer." (PMID 37501016, 2023). "Besides its potential as an applicant for targeted therapy, PET imaging using a 64Cu- or 89Zr-labeled monoclonal antibody against MSLN as well as subsequent therapeutical usage of anti-mesothelin antibody-drug conjugate treatment has shown promising results in pancreatic and/or ovarian cancer." (PMID 37047331, 2023). "In addition, multiple MSLN-directed antibody-drug conjugates (ADCs) have been developed, and some clinical trials have shown good tolerance and preliminary evidence of antitumor activity in ovarian cancer." (PMID 37209814, 2023). "Notably, studies have shown that mesothelin may play a key role in the adhesion and implantation of ovarian cancer cells into the peritoneal cavity." (PMID 36166071, 2023). "Given that MSLN is overexpressed in many solid tumours and has antigenic properties, this molecule could be considered an antigenic target for immunotherapeutic strategies in the treatment of ovarian carcinomas." (PMID 35565412, 2022). "Mesothelin is a glycosylphosphatidylinositol-anchored cell surface protein that has been identified in many different tumor types, including lung adenocarcinomas, ovarian carcinomas, and most recently in hematological malignancies, including acute myeloid leukemia (AML)." (PMID 35326701, 2022). "Notably, high mesothelin expression correlates with poor prognosis in ovarian cancer." (PMID 36046840, 2022). "Thus, the functions of MSLN in ovarian cancer treatment are worth further study." (PMID 35692779, 2022). "However, whether MSLN affects the drug resistance of ovarian cancer, and the related mechanisms of chemotherapy resistance are still unclear." (PMID 35692779, 2022). "Finally, as mentioned in the pancreatic cancer section, MSLN expression may be non-invasively evaluated in ovarian cancer, using 89Zr-labeled anti-MSLN Ab, which may help patient selection for therapy." (PMID 35836956, 2022). "Thus, in OC patients, CA125 may have a strong affinity for binding to mesothelin in ovarian cancer cells to trigger further effects that enhance metastasis." (PMID 33613114, 2021). "Additionally, MSLN is actively shed from the cell surface generating a pool of antigens in ascites or blood circulation allowing for the quantification of circulating serum MSLN levels potentially used for diagnosis of ovarian cancer patients." (PMID 30134520, 2018). "Therefore, blocking the MSLN-related pathway might be a potential therapeutic measure for the inhibition of ovarian cancer progression." (PMID 28538838, 2017). "Mesothelin (MSLN), a plasma membrane differentiation antigen, is expressed at significantly high levels in several human cancers, including nearly all mesotheliomas and pancreatic adenocarcinomas as wells as about 70% of ovarian cancers and 50% of lung adenocarcinomas." (PMID 22485139, 2012). "Metastatic ovarian cancer exhibited enhanced concurrent expression of MSLN and CA125 which is a noteworthy correlation between the manifestation of MSLN and CA125 as markers and the cancer progression." (PMID 40227616, 2025).
ovarian carcinoma (continued). "MSLN is a GPI-anchored protein bound to the cell surface that, because of its specific expression in ovarian cancer, also serves as a potential target for antigen-specific therapies as well as chimeric antigen receptor T-cell (CAR-T) therapies." (PMID 40792273, 2025). "Another advancement was the creation of anti-mesothelin CAR Vδ2 T cells, which showed effective targeting of ovarian cancer both in vitro and in vivo, with increased IL-15 expression further enhancing anti-tumor effects." (PMID 40148988, 2025). "Another example of an anti-cancer CAR γδ T cell is the anti-mesothelin CAR Vδ2 T cell enhanced with increased CD16 expression to augment ADCC, with or without additional increased IL-15 expression, for targeting ovarian cancers." (PMID 40148988, 2025). "MSLN was initially discovered in the OVCAR3 xenograft model and was identified as a specific antigen for ovarian cancer." (PMID 41400642, 2025). "Ovarian cancers often overexpress a range of TAAs such as FRα, mucin 16 [MUC16; cancer antigen 125 (CA-125)], and mesothelin, making them ideal targets for bsAb development." (PMID 41211166, 2025). "CAR-iMACS cells designed against CD19 and mesothelin were co-cultured with CD19+ K562 human leukaemic cells, mesothelin+ OVCAR3 human ovarian cancer cells, or mesothelin+ ASPC1 human pancreatic cancer cells." (PMID 40574837, 2025). "MSLN is markedly overexpressed in several malignancies, including pancreatic ductal adenocarcinoma (PDAC), ovarian cancer, non-small cell lung cancer (NSCLC), pleural mesothelioma (PM), and others." (PMID 41335396, 2025). "Mesothelin (MSLN), overexpressed in mesothelioma, pancreatic adenocarcinoma, and ovarian cancer, is another attractive target." (PMID 40624498, 2025). "Their investigation demonstrated that precisely modulating the activation of MSLN-CAR T cells resulted in enhanced and superior antitumor responses within the context of ovarian cancer models." (PMID 40849468, 2025). "The NCT03608618 trial is a phase 1, first-in-human, dose-escalation study assessing MCY-M11, a mesothelin-targeting CAR-M therapy, in patients with advanced ovarian cancer and malignant peritoneal mesothelioma." (PMID 40574837, 2025). "Tumour cell lines with MSLN expression (human gastric cancer cell line, AGS; human ovarian cancer cell line, A1847) were targets for specific cytotoxicity assay." (PMID 39136096, 2024). "A phase I/II clinical trial (NCT01583686) using anti-MSLN CAR-T cells in patients with metastatic solid tumors, including ovarian cancer, after pre-treatment with cyclophosphamide and fludarabine was terminated due to insufficient accrual after 6 years." (PMID 38667465, 2024). "used lentiviral vectors to generate anti-Mesothelin CAR-NK cells for the treatment of gastric and ovarian cancer and identified the efficient elimination of target cells in vitro and in vivo." (PMID 39781381, 2024). "While the immunosuppressive microenvironment of ovarian cancer has been a barrier in their implementation, several early phase clinical trials are currently evaluating CAR-T cell therapies targeting mesothelin, folate receptor a, HER2, MUC16, and B7H3." (PMID 38667465, 2024). "Among the CAR-T trials, multiple studies investigate the use of anti-Mesothelin CAR-T cells against gynecological cancers, focusing mainly on ovarian cancer." (PMID 39781381, 2024). "In this study, we confidently identified the marker combination of EEF1G + MSLN + BCAM + TAGLN2 which showed upregulation in both serum and tissue an outperforming marker panel against currently available markers for ovarian cancer." (PMID 38918474, 2024). "Some studies already assessed the feasibility of Mesothelin CAR-T cells, e.g., against pancreatic and ovarian cancer, and showed strong in vitro and in vivo anti-cancer effects." (PMID 39781381, 2024).
ovarian carcinoma (continued). "Additionally, EGCG was confirmed to enhance antigen-specific immunotherapy efficacy of mesothelin-specific chimeric DNA vaccine by boosting the maturation of DCs, which is promising to offer an effective approach for immunotherapy in malignant mesothelioma, ovarian cancer, and pancreatic cancer." (PMID 38348027, 2024). "A phase I of MSLN-targeting CAR T cells demonstrated anti-tumor activity in pancreatic ductal carcinoma, ovarian cancer, and malignant mesothelioma (NCT03054298 and NCT03323944)." (PMID 39835140, 2024). "Many investigated targets, such as mesothelin (MSLN), MUC-16, HER2, and folate receptor-α (αFR) are expressed in ovarian cancer tissue, which provides a basis for CAR-T development." (PMID 39431011, 2024). "Given the importance of their interaction for the tumorigenicity of ovarian cancer cells, MUC16 and mesothelin have emerged as putative targets for developing treatments for peritoneal metastasis in epithelial ovarian cancer." (PMID 38637885, 2024). "Later, with the help of western blot analysis, the authors found that the MSLN protein expresses higher in OVCAR-3 and SK-OV-3 human ovarian cancer cell lines and is almost negligible in the control human liver SKHEP-1 cancer cell line." (PMID 38694508, 2024). "Another preclinical study showed that the combination of anetumab ravtansine (a mesothelin-targeting ADC) with bevacizumab improved the anti-tumor activity in ST081 and OVCAR-3 human ovarian cancer models." (PMID 38178200, 2024). "In the case of ovarian cancer, research indicates that Mucin‐16 (MUC16) and Mesothelin (MSLN) are significant tumour antigens, presented respectively by human leukocyte antigen‐I and human leukocyte antigen‐II molecules." (PMID 38613345, 2024). "The expression of MUC16 in OCSC has been identified as the primary source of tumor metastasis and recurrence, and our study has confirmed the ability of MSLN-CAR T cells to recognize and eliminate CSCs derived from ovarian cancer cell lines that express MUC16." (PMID 38637885, 2024). "Another study utilized the dual recognition of mesothelin (with an anti-mesothelin scFv-CD3ζ to provide signal 1) and folic receptor alpha (FRα) (with an anti-FRα scFv-CD28 to provide signal 2) to target ovarian cancer." (PMID 38605087, 2024). "Preclinically, T cells targeting MSLN, CCNA1, CLDN6, and several MAGE-A family members have been investigated for ovarian cancer as well." (PMID 37026005, 2023). "The overexpression of MSLN in triple-negative breast cancer (TNBC), ovarian cancer, lung adenocarcinoma, cholangiocarcinoma and pancreatic cancer is related to poor prognosis." (PMID 36900151, 2023). "The MSLN expression on OVCAR3-FG, OVCAR8-FG, and SKOV3-FG was assessed, revealing variable MSLN expression in the three ovarian cancer models." (PMID 37938576, 2023). "There are multiple ongoing clinical trials evaluating ADCs in ovarian cancer, including those that target TROP2, mesothelin, and HER2." (PMID 37873862, 2023). "Recently, several CAR-T therapies for ovarian cancer have been explored, such as FOLR1, MSLN, TAG-72, and CD47." (PMID 37670338, 2023). "Elevated serum mesothelin values were observed in 12% of women with early-stage lesions (FIGO I, II) and in 48% of women with advanced stages of ovarian cancer (FIGO III and IV), with a test specificity of 95%." (PMID 37238197, 2023). "In the context of ovarian cancer CAR-T therapy, mesothelin can be named as the most researched target antigen, which has been the subject of various CAR-T-based preclinical and clinical investigations, which are briefly discussed in this section." (PMID 38146364, 2023). "hiPSC-derived macrophages have been engineered to express CD20-CAR with FcγR1, CD19, or mesothelin CAR with CD3ζ signaling domains, enabling them to destroy leukemic cells or ovarian cancers." (PMID 36638788, 2023).
ovarian carcinoma (continued). "A phase I clinical trial was conducted in patients with glypican-3 (GPC3) and mesothelin (MSLN)-positive advanced hepatocellular carcinoma (HCC), pancreatic cancer (PC), and ovarian cancer (OC)." (PMID 37190280, 2023). "ACOD1-/- MSLN-CAR-iMACs expressed more pro-inflammatory marker proteins (CD80 and CD86) after being co-cultured with HO-8910 ovarian cancer cells for 24 h." (PMID 37723178, 2023). "Second-generation CAR T cells were developed targeting mesothelin (MSLN), which is abundantly expressed in ovarian cancer." (PMID 36166071, 2023). "Signal intensities for the quantified proteins overall spanned approximately seven orders of magnitude and included several previously reported ovarian cancer marker candidates, such as HE4, MSLN, VCAM-1, CEA, CRP, PROZ, LCAT, and M-CSF." (PMID 36669591, 2023). "MCY-M11 was designed by delivery of mRNA into PBMCs to express anti-mesothelin-CAR and utilized in patients with advanced ovarian cancer and peritoneal mesothelioma." (PMID 38017494, 2023). "In a study on ovarian cancer, CAR-NK cells were designed to recognize mesothelin, and were effective in eliminating mesothelin+ cancer cells through increased cytokine secretion compared to the parental NK cell treatment." (PMID 35326701, 2022). "Regarding ovarian carcinoma (OvCa), Mucin-16 (MUC16) and Mesothelin (MSLN) were recently described as the top HLA class I- and HLA class II-presented tumor antigens, respectively." (PMID 35565389, 2022). "Currently, various early-stage MSLN-CAR T cell trials are ongoing, covering several malignancies including malignant pleural mesothelioma (MPM), pancreatic cancer, lung cancer and ovarian cancer." (PMID 35898704, 2022). "Thus, the combination therapy of this novel vaccine with PD-1 blockade may have great potential as a new treatment strategy for the treatment of other cancers, such as mesothelioma, pancreatic cancer, ovarian cancer and triple negative breast cancer with high expression of MSLN." (PMID 35795680, 2022). "Several studies have demonstrated the effectiveness of CAR-NK cell therapies targeting mesothelin, CD24 and glypican-3 in ovarian cancer models." (PMID 36324149, 2022). "Moreover, regarding the binding of MSLN to the ovarian cancer antigen CA125, which has been demonstrated in many studies, we also report on signal transduction pathways that may play an important role in the spread and neoplastic progression of this lethal neoplasm." (PMID 35565412, 2022). "The co-culture of ovarian cancer cells with MSLN knockout mesothelial cells resulted in a decreased size of multicellular aggregates, supporting the role of host mesothelin in tumor cell adhesion, migration, and metastasis." (PMID 35326701, 2022). "Mesothelin (MSLN) has emerged as an attractive target for CAR T cell therapy of several solid malignancies, including ovarian cancer." (PMID 35898704, 2022). "The well-known interacting partner of mesothelin is CA125/MUC16, a member of the mucin family of glycoproteins which is expressed in ovarian cancer and malignant mesothelioma." (PMID 35326701, 2022). "RC88, composed of anti-mesothelin mAb and MMAE, is being tested in a phase I clinical trial in mesothelin-positive solid tumor patients, including those with ovarian cancer." (PMID 36618922, 2022). "In ovarian cancer, CAR-T cells target folate-receptor alpha (FRα), mesothelin, MUC-1, and HER2 have been widely investigated." (PMID 36275669, 2022). "Our studies show that as an independent prognostic factor of ovarian cancer, MSLN participates in a variety of pathways related to suppressing immune activation and promoting chemotherapy resistance, which may provide a new perspective for immunotherapy of ovarian cancer." (PMID 35692779, 2022). "Mesothelin (MSLN) is a cell-surface glycoprotein, which is highly expressed in many cancers, including malignant mesothelioma, pancreatic cancer, and ovarian cancer." (PMID 36434635, 2022).